CLIC1 (CLIC family member 1)
Diseases named in the same sentence as CLIC1 in open-access papers (continued):
Sharing a sentence is not in itself a finding about the gene and the disease.
ovarian carcinoma (continued). "Results presented herein suggest CLIC1 may be a potential therapy target in ovarian cancer, contributing to the diagnosis and treatment of ovarian cancer." (PMID 27825122, 2016). "CLIC1 and LGALS3BP were strongly expressed in 13 ovarian cancer tissues compared with normal ovary tissues by immunohistochemistry." (PMID 27825122, 2016). "The up regulation of CLIC1 and LGALS3BP in ovarian cancer tissues in quantitative proteomics were verified by western blotting and immunohistochemistry." (PMID 27825122, 2016). "Studies have shown two members of the CLIC protein family, CLIC1 and CLIC4, to be significantly upregulated in EOC patients compared to healthy controls, and shed into the blood of ovarian cancer patients." (PMID 35223789, 2022). "Expression levels of CLIC1 and CLIC4 have also been implicated in patient survival, with elevated CLIC4 expression a negative indicator of patient survival in ovarian cancer." (PMID 35223789, 2022). "The expression levels of chloride intracellular channel protein 1 (CLIC1) and lectin galactoside-binding soluble 3 binding protein (LGALS3BP) in epithelial ovarian cancer tissues were significantly higher than those in normal ovary tissues as confirmed by western blotting and immunohistochemistry." (PMID 27825122, 2016). "The up-regulation of two proteins, chloride intracellular channel protein 1 (CLIC1) and lectin galactoside-binding soluble 3 binding protein (LGALS3BP), were found in ovarian cancer tissues by quantitative proteomics and confirmed by immunohistochemistry and western blotting." (PMID 27825122, 2016). "Low or high CLIC1 expression in the lung or ovarian cancers does not influence patient survival." (PMID 32116799, 2020). "CLIC1 and LGALS3BP were knocked down by shRAN separately in A2780 cells, but unfortunately the knockdown of LGALS3BP in ovarian cancer cells showed no significant phenotypes." (PMID 27825122, 2016).
pancreatic cancer (11 papers, 2007 to 2025). "Markedly, it has been reported that changes in CLIC1 are associated with poor prognoses in patients with gall cancer, pancreatic cancer, epithelial ovarian cancer, and hepatic cancers." (PMID 36727059, 2022). "This study demonstrated that CLIC1 expression is integral to the development and progression of pancreatic cancer." (PMID 36826036, 2023). "In various regulatory processes involving CLIC1, small interfering (si)RNAs of CLIC1 induce the downregulation of cell proliferation, growth, and invasiveness of pancreatic cancer cell lines such as PANC-1 and MIAPaca-2 compared with control cells." (PMID 35205604, 2022). "This work ascertains that CLIC1 expression is integral to the development and progression of pancreatic cancer." (PMID 32116799, 2020). "CLIC1 has been noticed to be overexpressed in pancreatic neoplasms." (PMID 36826036, 2023). "Lu and colleagues have postulated that CLIC1 acts as an oncogene in pancreatic cancer." (PMID 34357102, 2021). "CLIC1 was also shown to be overexpressed in pancreatic cancer tissues." (PMID 32116799, 2020). "As for CLIC1 and CLIC2 proteins, also CLIC3 was found to be overexpressed in bladder cancer, pancreatic cancer, and metastatic breast cancer." (PMID 34357102, 2021).
Alzheimer disease (9 papers, 2020 to 2026). A progressive, neurodegenerative disease characterized by loss of function and death of nerve cells in several areas of the brain leading to loss of cognitive function such as memory and language. "Recent studies have shown that in Alzheimer’s disease, the activation of chloride intracellular channel 1 (CLIC1) is necessary for β-amyloid-induced production of reactive oxygen species by microglia." (PMID 37801482, 2023). "Blood RNA levels showed that CLIC1 was the only significant probe to change among groups although, to date, it cannot be sufficient to predict neurodegenerative progression throughout Alzheimer’s Disease." (PMID 34357102, 2021). "At the functional level, CLIC1 is characterized for its role in Alzheimer’s disease (AD) where it is present in activated microglia." (PMID 32116799, 2020). "Furthermore, a recent study elucidates the regulatory role of circAPP in Alzheimer’s disease via the miR-1906/CLIC1 axis during microglial polarisation." (PMID 40966238, 2025). "In a recent study it was shown that peripheral blood mononuclear cells (PBMC) and, in particular, monocytes, isolated from Alzheimer’s Disease patients show an overexpression of CLIC1 mRNA that is accompanied by a significative increase in transmembrane protein." (PMID 34357102, 2021). "Chloride intracellular channel 1 (CLIC1) contributes to the pathogenesis of cancer and Alzheimer’s disease." (PMID 37669116, 2023). "Furthermore, members of the CLIC family, CLIC1 to CLIC6 are also involved in pathological conditions, like cancer initiation and progression, cardiac dysfunction, and Alzheimer’s Disease (AD)." (PMID 37601094, 2023).
gallbladder cancer (7 papers, 2010 to 2023). "CLIC1 is found to be significantly up-regulated in highly metastatic gallbladder carcinoma cell lines." (PMID 21040583, 2010). "Modulation of CLIC1 expression by micro RNA, hsa-mir-372 predicts the poor prognosis of patients affected with gall bladder cancers and is important for the migration and invasion of gall bladder cancer cells." (PMID 32116799, 2020). "Interestingly, a similar effect of metformin on CLIC1 activity was independently reported in gallbladder cancer cells, further confirming our evidence." (PMID 30186163, 2018).
lung carcinoma (7 papers, 2018 to 2025). "In lung cancer, CLIC1 overexpression is associated with increased tumor growth and angiogenesis." (PMID 37984883, 2024). "CLIC1 and other types of chloride channels could be potential treatment strategies for cancer and should be considered as novel diagnostic and therapeutic targets for prostate, gastric, gallbladder, colon, pancreas, lymphatic, and lung cancers." (PMID 35205604, 2022). "Upregulated CLIC1 expression correlates with lymph node metastasis and lymphatic invasion as well as lung cancer migration and invasion." (PMID 35205604, 2022). "In this study, we investigated the function of CLIC1 in Ca2+ and ROS signaling in A549 human lung cancer cells." (PMID 31316050, 2019). "Hana Cho from Sungkyunkwan University School of Medicine in Suwon, South Korea, and colleagues inhibited the CLIC1 chloride channel in human lung cancer cells and observed increased activity of a calcium channel." (PMID 31316050, 2019). "We found that depletion of CLIC1 with shRNA in A549 human lung cancer cells increased DNA double-strand breaks both under control conditions and under treatment with the putative anticancer agent chelerythrine, with a concomitant increase in p-JNK levels." (PMID 31316050, 2019). "In this study, we investigated the role of CLIC1 and its molecular mechanism in A549 human lung cancer cells." (PMID 31316050, 2019). "Similar to its effect in human esophageal squamous cell carcinoma, CLIC1 knockdown in A549 human lung cancer cells upregulated cell death and JNK activation concomitant with the elevated ROS levels." (PMID 31316050, 2019). "Among them, CLIC1, CLIC3, and CLIC4 have been investigated more extensively, particularly in the context of lung cancer, inflammatory diseases, and pulmonary arterial hypertension." (PMID 41907764, 2025).
bladder cancer (6 papers, 2016 to 2024). "As a result of the mass spectrometry results, CLIC1 was identified as a potential target associated with bladder cancer T stage." (PMID 36727059, 2022). "For validation, immunohistochemical (IHC), qPCR, and western blotting (WB) were performed.Further, we found that CLIC1 was associated with a poor prognosis of bladder cancer in survival analysis." (PMID 36727059, 2022). "In this investigation, CLIC1 was highly expressed in bladder cancer tissues and circulated in the blood." (PMID 36727059, 2022). "CLIC1 expression in bladder cancer tissue was 84% positive, of which 26% were weak positives (+), 50% were moderate positives (++), and 8% were strong positives (+++)." (PMID 36727059, 2022). "According to our knowledge, Our research screened CLIC1 as a tumor-promoting protein in bladder cancer for the first time using serum mass spectrometry." (PMID 36727059, 2022). "CD8 T cells were discovered to be more infiltrated in bladder cancers from groups with faint CLIC1 expression." (PMID 36727059, 2022). "Further research is needed to clarify the precise role CLIC1 plays in bladder cancer and investigate its potential contribution to bladder cancer prognostication." (PMID 36727059, 2022). "Cell lines derived from bladder cancer possessed higher levels of CLIC1 expression than normal uroepithelium cells and were examined via RT-qPCR and western blotting." (PMID 36727059, 2022). "Our research screened CLIC1 as a tumor-promoting protein in bladder cancer for the first time using serum mass spectrometry." (PMID 36727059, 2022). "Kaplan-Meier survival curve and log-rank tests showed higher expression levels of CLIC1 were significantly correlated with poor patient outcomes based on 50 bladder cancer patients." (PMID 36727059, 2022). "The high expression of CLIC1 in bladder cancer tissue is consistent with previous studies." (PMID 36727059, 2022). "However, CLIC1’s clinical significance in bladder cancer has yet to be determined." (PMID 36727059, 2022). "The prognostic biomarker and therapeutic target CLIC1 may be new for bladder cancer patients." (PMID 36727059, 2022). "In studies of bladder cancer prognostic markers, Wang found that CLIC1, as a prognostic marker, showed a negative correlation with CD8+ T cells." (PMID 38299141, 2023). "Notably, CLIC1 alterations have been observed in solid tumors and vascular malformations, particularly in GBM and bladder cancers." (PMID 38027011, 2023). "Among 50 bladder cancer tissue specimens, we found that eight patients had CLIC1- negative positives, 13 weak positives, 25 moderate positives, and four patients were strong positives." (PMID 36727059, 2022).
breast carcinoma (6 papers, 2012 to 2025). "This indicates CLIC1’s potential as a diagnostic marker for breast cancer." (PMID 38027011, 2023). "In breast cancer, Xia found that the expression of CLIC1 was increased at both RNA and protein levels." (PMID 41142627, 2025). "CLIC1 has been shown to promote cell proliferation and invasion in breast cancer by activating the Wnt/β‐catenin signaling pathway." (PMID 37984883, 2024). "Microarray studies have identified changes in CLIC5 and CLIC6 expression in breast cancer tissues along with CLIC1 and CLIC4." (PMID 32116799, 2020). "Breast cancer shows heightened CLIC1 expression, correlating with tumor characteristics such as size, TNM classification, pathological grade, lymph node metastasis, and Ki67, while lower expression levels associate with extended overall survival and progression-free survival." (PMID 38027011, 2023). "In breast cancer, elevated CLIC1 expression correlates with tumor characteristics like size, TNM classification, grade, lymph node metastasis, and Ki67, while lower expression associates with extended OS and progression-free survival, suggesting its diagnostic potential." (PMID 38053842, 2023).
esophageal squamous cell carcinoma (6 papers, 2018 to 2025). Esophageal squamous cell carcinoma (ESCC) is a type of esophageal carcinoma (EC) that can affect any part of the esophagus, but is usually located in the upper or middle third. "In esophageal squamous cell carcinoma (ESCC), CLIC1 is linked to clinical TNM classifications." (PMID 38053842, 2023). "Chloride intracellular channel 1 (CLIC1) is also reported to be a key factor in cell proliferation of esophageal squamous cell carcinoma." (PMID 37968609, 2023). "However, CLIC1 knockdown in human esophageal squamous cell carcinoma induced apoptosis through the JNK pathway, likely reflecting excessive ROS production." (PMID 31316050, 2019). "However, CLIC1 can also function as a negative regulator of ROS in other tumors, since the depletion of CLIC1 using siRNA in human esophageal squamous cell carcinoma induced apoptosis via the JNK pathway, which is strongly associated with excessive ROS production." (PMID 31316050, 2019). "However, the expression and role of CLIC1 in human esophageal squamous cell carcinoma (ESCC) remains unknown." (PMID 29796185, 2018). "Notably, Kobayashi demonstrated that the absence of CLIC1 hindered cell proliferation and triggered apoptosis in esophageal squamous cell carcinoma (ESCC)." (PMID 40948771, 2025).
liver cancer (6 papers, 2018 to 2023). An epithelial or non-epithelial malignant neoplasm that arises from the liver. "In liver cancer, miR-124 overexpression reduces the expression of CLIC1, thereby reducing the migration and invasion of liver cancer cells." (PMID 32873299, 2020). "Kaplan-Meier (K-M) analysis of the data collected from several human cancers showing patient survival as a function of the relative mRNA levels (high, red or low, black) indicates CLIC1 high expression correlates to poor patient survival in pancreatic, breast and liver cancers." (PMID 32116799, 2020).
colorectal cancer (5 papers, 2019 to 2025). A primary or metastatic malignant neoplasm that affects the colon or rectum. "In colorectal cancer, Petrova found that the CLIC1 protein is significantly overexpressed in cancer tissues and indicate that CLIC1 is a biomarker for colorectal cancer." (PMID 41142627, 2025). "According to “The Human Protein Atlas” RNA database, gliomas, colorectal cancer, lung, ovarian, pancreatic, prostate, breast, and melanoma cancers have shown higher levels of CLIC1 RNA." (PMID 34357102, 2021). "In addition, CLIC1 protein upregulation correlates with the level of aggressiveness and metastatic potential of colorectal cancer cells, where it was demonstrated to regulate cell volume and ROS level." (PMID 34357102, 2021).
prostate carcinoma (4 papers, 2018 to 2025). A carcinoma that arises from epithelial cells of the prostate gland. "Additional cancer-associated genes affected by promoter-associated risk alleles include CLIC1, which facilitates prostate cancer proliferation and migration; MICA, which enhances immune evasion mechanisms; and UHRF1 BP1, which supports prostate tumor progression through epigenetic regulation." (PMID 41468516, 2025). "Cell growth is promoted by CLIC1 via the MAPK/ERK pathway in prostate cancer and CLIC1 is expressed in pancreatic ductal adenocarcinoma (PDAC) where it plays an important role in promoting cancer cell survival, proliferation, and invasion." (PMID 35205604, 2022). "From this list, PABPC1, CLIC1, RAB10, and PKM2 have been identified as a potential marker for (prostate) cancer." (PMID 31018022, 2019).
gastric adenocarcinoma (3 papers, 2021 to 2023). "The CLIC1 alteration was found as following: gastric adenocarcinoma cases (3.86%), pancreatic adenocarcinoma cases (2.17%) and colorectal adenocarcinoma cases (1.01%)." (PMID 36826036, 2023). "Knockdown of PSME2 is involved in the invasion and metastasis of gastric adenocarcinoma through upregulation of the chloride intracellular channel 1 (CLIC1)." (PMID 36226063, 2022). "No results were found in TCGA databases regarding CLIC1 alteration in liver metastases of colorectal, pancreatic and gastric adenocarcinoma." (PMID 36826036, 2023).
lung adenocarcinoma (3 papers, 2012 to 2023). A carcinoma that arises from the lung and is characterized by the presence of malignant glandular epithelial cells. "High CLIC1 expression in lung adenocarcinoma has been linked to reduced overall survival, establishing it as an independent prognostic factor." (PMID 38027011, 2023). "High CLIC1 expression in lung adenocarcinoma predicts shorter overall survival and functions as an independent prognostic factor." (PMID 38053842, 2023).
lymph node metastasis (3 papers, 2018 to 2023). "The very weak expression of CLIC1 correlated with age and histological type, but not with other clinicopathological variables, including gender, recurrence, tumor length, lymphatic invasion, venous invasion, pathological depth of the tumor, and pathological lymph node metastasis." (PMID 29796185, 2018).
medulloblastoma (3 papers, 2022 to 2023). A malignant, invasive embryonal neoplasm arising from the cerebellum. "For example, the chloride intracellular channel 1 (CLIC1) cooperates with the potassium channel Kv10.2 (also called EAG2) in promoting the growth of medulloblastoma cells, and their simultaneous silencing synergistically suppresses tumor growth." (PMID 37175655, 2023). "In a recent report, CLIC1 was shown to interact with the potassium channel EAG2 to promote the growth of medulloblastoma by regulating cell volume, identifying CLIC1 and EAG2 as potential therapeutic targets." (PMID 35727842, 2022).
Arthritis (2 papers, 2012 to 2016). Inflammation of a joint. "Our observation that the CLIC1 gene (chloride intracellular protein) is expressed in RASFs correlates with the finding that CLIC1(-/-) mice were protected from development of serum transfer induced K/BxN arthritis." (PMID 23259760, 2012). "CLIC1 ablation impaired the capacity of phagosomal proteolysis and reduced ROS through its ion channel activity in CLIC1−/− macrophages, and similarly, CLIC1−/− mice were protected from K/BxN arthritis, both suggesting that CLIC1 is a suitable target for anti-inflammation." (PMID 27861612, 2016).
atrial fibrillation (2 papers, 2025 to 2026). A disorder characterized by an electrocardiographic finding of a supraventricular arrhythmia characterized by the replacement of consistent P waves by rapid oscillations or fibrillatory waves that vary in size, shape and timing and are accompanied by an irregular ventricular response. "Previous studies have reported the involvement of CLICs (CLIC1, CLIC4, CLIC5) in atrial fibrosis and remodeling in atrial fibrillation (AF)." (PMID 41521401, 2026). "For example, CLIC1 upregulates in CD8 T cells and natural killer cells in atrial fibrillation thrombi, indicating its potential involvement in cytotoxic activity and tissue injury, thereby posing a risk of cardioembolic stroke." (PMID 40966238, 2025).
autoimmune disease (2 papers, 2016 to 2022). A disorder resulting from loss of function or tissue destruction of an organ or multiple organs, arising from humoral or cellular immune responses of the individual to their own tissue constituents. "Further, they indicate that CLIC1 is a novel therapeutic target to help reduce the adaptive immune response in autoimmune diseases." (PMID 27113959, 2016).
Autoimmunity (2 papers, 2016 to 2017). The occurrence of an immune reaction against the organism's own cells or tissues. "In the case of autoimmunity, where these processes are dysregulated resulting in immune mediated tissue destruction, CLIC1 may represent a novel therapeutic target." (PMID 27113959, 2016).
brain tumors (2 papers, 2015 to 2019). "Moreover, increasing evidence shows that modification of microglia ion channel activity, and CLIC1 in particular, contributes to the development of different neuropathological states and brain tumors." (PMID 30918838, 2019).
cardiac hypertrophy (2 papers, 2021 to 2026). "The study findings further emphasized the possible roles of CLICs, particularly CLIC1, CLIC4, and CLIC5, in cardiac hypertrophy and heart failure." (PMID 41521401, 2026). "We speculate that CLIC1 is involved in the progression of HCM by regulating the generation of ROS and might be a potential therapeutic target for cardiac hypertrophy." (PMID 34054926, 2021).
clear cell renal carcinoma (2 papers, 2019 to 2022). A malignant epithelial neoplasm of the kidney characterized by the presence of lipid-containing clear cells within a vascular network. "Only a few articles indicate CLIC1 expression in tumor BVs endothelium, and none mention CLIC1 expression in neo-vessels from clear cell renal cell carcinomas (ccRCC)." (PMID 36497464, 2022).